EZH2 (enhancer of zeste 2 polycomb repressive complex 2 subunit)
Diseases named in the same sentence as EZH2 in open-access papers (continued):
Sharing a sentence is not in itself a finding about the gene and the disease.
gastric cancer (continued). "Moreover, in gastric cancer cells, EZH2 can bind to the promoter region of tumor suppressor gene P21 and mediate H3K27me3 modification, resulting in the transcriptional silencing of P21, which, in turn, promotes the proliferation of gastric cancer cells." (PMID 40959108, 2025). "MiR-217 could inhibit gastric cancer progression and metastasis by regulating enhancer of zeste 2 polycomb repressive complex 2 subunit (EZH2)." (PMID 38709402, 2024). "EZH2, a histone methyltransferase subunit of a Polycomb repressor complex, is upregulated in a variety of human malignancies, such as prostate, breast, and gastric cancers." (PMID 39013911, 2024). "Epigenetic modifications can be reversed, thus targeting DNMTs and EZH2 could offer a promising therapeutic approach for gastric carcinoma." (PMID 38542354, 2024). "It was reported that EZH2 is highly expressed in gastric cancer and may be a potential prognostic molecule and promising therapeutic target." (PMID 36672374, 2023). "Furthermore, EZH2 inhibition has been shown to provide a specific vulnerability for ARID1A-mutated ovarian and gastric cancers, further supporting the interactions between writers and readers in cancer." (PMID 36653445, 2023). "In addition, targeted inhibition of EZH2 expression can effectively delay the progression of gastric cancer and improve its resistance to chemotherapeutic agents." (PMID 36672374, 2023). "As a tumor-suppressor, miRNA-26 suppresses EZH2 expression to impair gastric cancer progression." (PMID 35236381, 2022). "In gastric cancer cells EZH2 promotes EMT, upregulates Vimentin and downregulates E-cadherin." (PMID 36316365, 2022). "Similarly,it has already been reported in anothor study that lncRNA PVT1 inhibite the proliferation of gastric cancer by combining with enhancer of zeste homolog 2 (EZH2) to repress p15 and p16." (PMID 35392800, 2022). "Moreover, over-expressed NEAT1 combined with the enhancer of zeste homologue 2 (EZH2) to upregulate the expression of downstream genes of EZH2, thereby promoting gastric cancer invasion and metastasis." (PMID 35628623, 2022). "Gastric cancer is a lethal disease and EZH2 upregulation is in favor of gastric carcinogenesis." (PMID 35236381, 2022). "Moreover, the target relation between miR‐126 and EZH2 in chemosensitivity in gastric cancer cells has been proved previously." (PMID 35322532, 2022). "Moreover, our previous study revealed that pseudogene DUXAP10 is over-expressed in gastric cancer, and promoted cell proliferation and invasion via interacting with EZH2 and LSD1 to repress LATS1 transcription." (PMID 34660601, 2021). "For instance, lncRNA PCAT-1, a highly expressed lncRNA in DDP-resistant gastric cancer tissues and cells, promotes DDP resistance of gastric cancer cells via epigenetically suppressing PTEN expression by recruiting EZH2, as well as regulating the miR-128/ZEB1 axis." (PMID 32192494, 2020). "LncRNA-LET was a target gene of DANCR, and DANCR could associate with enhancer of zeste homolog 2 (EZH2) and HDAC3 to epigenetically silence lncRNA-LET, then regulate gastric cancer migration and invasion." (PMID 33123287, 2020). "EZH2 could bind to P21 promoter region and mediate H3K27me3 modification, resulting in transcriptional silencing of P21, and promoting proliferation of gastric cancer cells." (PMID 32723346, 2020). "Interestingly, knockdown of EZH2 also resulted in increased LATS2 expression in gastric cancer cells." (PMID 32157157, 2020). "Second, PVT1 could also alter the expression of certain genes, including bind to EZH2 in non-small cell lung cancer and gastric cancer." (PMID 30083911, 2019). "Therefore, Ezh2 provides new perspectives for research of cell regulation in gastric cancer and new targets for gastric cancer diagnosis and treatment." (PMID 29335012, 2018). "Moreover, TUG1 has been proved to regulate genes expression by binding with EZH2 in human non-small cell lung cancer, gastric cancer and hepatocellular carcinoma." (PMID 30519392, 2018).
gastric cancer (continued). "For example, lncRNA urothelial cancer associated 1 (UCA1) is upregulated in gastric cancer tissues, and promotes the growth and cell cycle process through binding to enhancer of zeste 2 polycomb repressive complex 2 subunit (EZH2) and facilitating cyclin D1 expression in gastric cancer cells." (PMID 29773901, 2018). "For instance, XIST is upregulated in gastric cancer and inhibits expression of EZH2." (PMID 29100288, 2017). "CYTOR could promote gastric cancer cell cycle progression through binding to EZH2 and regulating p15 and p21." (PMID 29108264, 2017). "Moreover, increased LINC00152 promoted cell growth and cell cycle progression in gastric cancer by repressing p15 and p21 transcription through binding EZH2." (PMID 28109288, 2017). "Additionally, gastric cancer progression is associated with the lncRNA LINC00673 through the interaction with LSD1 and EZH2, leading to inhibition of KLF2 and LATS2 expression to exert oncogenic functions in vitro and in vivo." (PMID 28561778, 2017). "However, MALAT1 can bind to EZH2 and then induces cancer malignant development in aggressive renal cell carcinoma cells, esophageal squamous cell carcinoma cells and gastric cancer cells in vitro and in tumor tissue samples." (PMID 28561778, 2017). "To determine whether ZFAS1 repressed NKD2 and KLF2 expression via interacting with EZH2 or LSD1 in gastric cancer cells, we evaluated their expression after knockdown of EZH2 and LSD1 in gastric cancer cells." (PMID 27246976, 2017). "Overexpression of H3K27me3 and the methyltransferase EZH2 (Enhancer of zeste homolog 2) have been shown to be independent prognostic factors for predicting survival in gastric cancer, and utilized together could potentially predict lymph node metastasis." (PMID 28075351, 2017). "lncRNA XIST is up-regulated and is associated with aggressive tumor phenotypes and patient survival in gastric cancer, and the newly identified lncRNA XIST/miR-101/EZH2 axis could be a potential biomarkers or therapeutic targets for gastric cancer patients." (PMID 27620004, 2016). "As determined in our meta‐analysis, we concluded that EZH2 overexpression was associated with poor OS in oesophageal cancer, but not among gastric cancer or colorectal cancer." (PMID 26859127, 2016). "Furthermore, to investigate the roles of EZH2/SUZ12 in gastric cancer, we performed qRT-PCR analysis and found that EZH2/SUZ12 expression was significantly increased in 30 pairs of gastric cancer tissues." (PMID 27036039, 2016). "Additionally, other work suggested that histone methyltransferase EZH2 depletion promotes cellular senescence by activation of p21 in gastric cancer cells." (PMID 27129219, 2016). "EZH2 has been found to be involved in multiple tumors, including gastric cancer." (PMID 27620004, 2016). "Thus, we conducted a meta‐analysis of all available studies relating EZH2 with the clinical outcome in patients with digestive cancers including oesophageal cancer, gastric cancer and colorectal cancer." (PMID 26859127, 2016). "Moreover, the restoration of EZH2 expression in cells stably expressing miR-217 (SGC7901/miR-217) was able to counteract the inhibitory effects of miR-217 in the gastric cancer cells." (PMID 25869101, 2015). "In our study, we showed high abundance binding between PVT1 and EZH2 in gastric cancer cells, and we further confirmed that PVT1 could mediate epigenetic regulation of p15 and p16 in Trans." (PMID 25890171, 2015). "Moreover, EZH2 overexpression has been shown to contribute to gastric cancer invasion and metastasis." (PMID 25869101, 2015). "In our previous study, we showed that miR-124 could sensitize human gastric cancer cells to 5-FU-induced apoptosis by downregulating EZH2 expression." (PMID 26504803, 2015).
gastric cancer (continued). "It has been found that miR-124 can inhibit the proliferation of gastric cancer cells by directly targeting the EZH2 gene, and miR-124 has an additive effect with conventional chemotherapy 5-fluorouracil (5-FU), which has the potential to become a new treatment method for gastric cancer." (PMID 40296904, 2025). "However, the current research on the relationship between the gene polymorphisms in EZH2 and gastric cancer is not comprehensive enough, and the research area of relevant experiments is also limited and needs further research." (PMID 36672374, 2023). "Therefore, in this review, we present the two main functions of EZH2: histone methylation modification and DNA methylation by EZH2; the molecular mechanism of the action of EZH2 in regulating target genes; a detailed description of the mechanism of EZH2 in gastric cancer-related events." (PMID 36672374, 2023). "Also, elevated EZH2 expression was revealed in gastric cancer tissues." (PMID 35668081, 2022). "Finally, we found that the imbalance of 11 immune regulatory factors could predict the overall survival time of gastric cancer, including EZH2, NRP1, CD59, OsBPL1aBCL11B, BASP1, HNMT, CXCR4, ASGR2, ANXA5, CDH2." (PMID 34322132, 2021). "Additionally, in gastric cancers EZH2, a methyltransferase and the core catalytic subunit of polycomb repressive complex 2, may mediate the epigenetic suppression of EPHB3." (PMID 32294981, 2020). "In addition, ectopic expression of miR-126, miR-647 and miR-1284, which are evidently downregulated in drug-resistant SGC7901/VCR gastric cancer cells, could sensitize gastric cancer cells to VCR by inhibiting expression of EZH2, ANK2 and EIF4A1, respectively." (PMID 32192494, 2020). "It has been reported that MALAT1 associates with EZH2 and enhanced methylation of H3K27 to downregulate genes in renal cancer cells; on the other hand, MALAT1 upregulates EGFL7 by altering the level of H3 histone acetylation at EGFL7 promoter in gastric cancer." (PMID 29511340, 2018). "In addition, LINC00673 regulates target gene expression in gastric cancer cells by recruiting histone methyltransferase EZH2 and demethylase LSD1 to target gene promoters, suggesting that it can function as a transcriptional regulator through epigenetic mechanisms." (PMID 29262782, 2017). "Therefore, we provided the first evidence that knockdown of lncRNA XIST could inhibit gastric cancer progression and metastasis by modulating the miR-101/EZH2 pathway." (PMID 27620004, 2016). "We first confirmed that miR-101 could negatively regulate EZH2 expression in gastric cancer cells." (PMID 27620004, 2016). "In this study, we performed a transcriptome-wide profiling of EZH2-bound transcripts in human gastric cancer (GC) cell lines with modified RIP-seq and explored how EZH2 is involved in gastric tumorigenesis through its interaction with RNAs." (PMID 26871474, 2016). "Moreover, restoration of the expression of EZH2 in gastric cancer cells stably expressing miR-217 was able to counteract the tumor-suppressive effects of miR-217, whereas the knockdown of EZH2 in these cells was able to mimic the tumor suppressive effects of miR-217." (PMID 25869101, 2015). "EZH2, a specific histone-lysine N-methyltransferase, inhibits cycle arrest in NSCLC cells and gastric cancer cells." (PMID 41154714, 2025). "Apigetrin exerted its cytotoxic effects in gastric cancer cells by initiating autophagy-driven cell death through the inhibition of HIF-1α and EZH2 in both hypoxic and normoxic environments." (PMID 41155376, 2025). "Studies have shown that in mouse models, inflammation-driven downregulation of EZH2 maintains SASP in CAFs by demethylating the H3K27me3 mark and enhances the formation of peritoneal tumors in gastric cancer (GC) through the JAK/STAT3 signaling pathway." (PMID 40755775, 2025).
gastric cancer (continued). "According to this study’s findings, LINC00460 influences gastric cancer cell proliferation and apoptotic activity via the downregulation of CCNG2 and recruiting LSD1 and EZH2." (PMID 38850527, 2024). "EZH2 trimethylates histone H3 at lysine 27, leading to gene-expression control and contributing to SRBC gene downregulation in gastric-cancer tissues." (PMID 38542354, 2024). "We finally verified the mRNA expression of EZH2, G6PD, LGALS3 and PSMD14 by qRT-PCR in clinical gastric cancer tissue samples." (PMID 37853322, 2023). "By increasing EZH2 expression, LINC01303 can inhibit the activity of miR-101-3p, thereby inducing the proliferation, migration, and invasion of gastric cancer cells." (PMID 37361568, 2023). "In a mouse model, the pro-inflammatory cytokine-driven downregulation of EZH2 maintains SASP by demethylating H3K27me3 marks and promotes peritoneal tumor formation in gastric cancer (GC) via JAK/STAT3 signaling." (PMID 37049920, 2023). "These include the action of PCAT-1 (Prostate Cancer-Associated Transcript 1), which epigenetically silenced PTEN (Phosphatase and Tensin Homolog) via recruiting EZH2 in BGC823/CDDP and SGC7901/CDDP cisplatin-resistant gastric cancer cell lines." (PMID 36230683, 2022). "LRP4 is overexpressed in papillary thyroid and gastric cancers, where it promotes EMT through PI3K/AKT pathwayand modulation of N-cadherin, ZEB1 and EZH2." (PMID 36012187, 2022). "Evidence has revealed that OIP5-AS1 aggravated cell growth and migratory ability via interaction with EZH2 and downregulation of NLRP6 in gastric cancer." (PMID 35756672, 2022). "EZH2 as an upstream mediator down-regulates miRNA-125a and BRMS1 to enhance gastric cancer metastasis." (PMID 35236381, 2022). "PCAT1 physically binds to enhancer of Zeste 2 polycomb repressive complex 2 subunit (EZH2) and, thus, epigenetically silences PTEN expression, leading to cisplatin resistance in gastric cancer." (PMID 35055115, 2022). "This study demonstrated that H2 gas curbed gastric cancer growth in vivo and gastric cancer cell proliferation and migration in vitro by reducing lncRNA MALAT1 level, which in turn upregulated miR-124-3p and downregulated EZH2 expression." (PMID 33482814, 2021). "In Gastric Cancer, LINC00673 regulates Oncogenic biological behavior by Interacting with LSD1 and EZH2." (PMID 34811354, 2021). "In gastric cancer, STAT3 was shown to bind to EZH2 promotor and to increase EZH2 following IL6 stimulation." (PMID 34857028, 2021). "Two lncRNAs interacting with EZH2, lncRNA AFAP1-AS1, and LINC00673 are reported to be involved in the migration of gastric cancers." (PMID 33050646, 2020). "In gastric cancer, the expression of P21, PLK3, and DDZT3 is inhibited by binding of HOXA-AS2 to EZH2, which promotes tumor proliferation and inhibits tumor cell apoptosis." (PMID 32760226, 2020). "HOXA11-AS1/WDR5, EZH2, and STAU1 boost metastasis in gastric cancer through regulation of their respective target genes." (PMID 33050646, 2020). "Another methyltransferase (EZH2) is regulated by STAT3 and participates in anti-apoptosis in gastric cancer cells." (PMID 33023006, 2020). "PVT1 has been shown to recruit Enhancer of Zeste homolog 2 (EZH2) to epigenetically negatively regulate the expression of p15 and p16 in gastric cancer cell lines." (PMID 32083000, 2020). "It has been recently reported that STAT3 can bind to the promoter region of the EZH2 gene in gastric cancer cells, implicating STAT3 as a direct regulator of EZH2." (PMID 33086505, 2020). "AGAP2-AS1 was demonstrated as an oncogenic lncRNA in NSCLC and gastric cancer by interacting with LSD1 and EZH2." (PMID 31186379, 2019). "In gastric cancer (GC), HOTAIR epigenetically silences miR-34a by binding the PRC2 (polycomb repressive complex 2) component EZH2 to promote EMT progression." (PMID 31575017, 2019).
gastric cancer (continued). "LINC00668 enhances gastric cancer cell proliferation by binding to PRC2 and activating EZH2 to silence CKIs, partially accounting for LINC00668-mediated cell growth regulation." (PMID 29721215, 2018). "In gastric cancer, HOXA11-AS not only acts as a scaffold for EZH2, LSD1 and DNMT1 but also functions as a molecular sponge for miR-1297 to antagonize its repressive effect on EZH2 translation." (PMID 29721215, 2018). "Proteins interacting with CYTOR had been investigated in other cancer types; for example, EZH2 and EGFR were reported to interact with CYTOR in gastric cancer." (PMID 30064438, 2018). "Mechanistically, EZH2 and LSD1 (histone demethylase) are recruited by HOXA11-AS, which acts as a scaffold to form the EZH2/HOXA11-AS/LSD1 axis, a critical effector in gastric cancer tumorigenesis and progression." (PMID 29721215, 2018). "Three target genes (EZH2, YWHAZ and RUNX1) were upregulated in gastric cancer compared to normal gastric mucosa." (PMID 30258124, 2018). "In gastric cancer progression, Long non-coding RNA LINC00673 is activated by SP1 and exerts oncogenic properties by interacting with LSD1 and EZH2." (PMID 29221147, 2017). "Aberrant expression of MALAT1 was confirmed to bind EZH2, suppressed the tumor suppressor PCDH10, and promoted gastric cancer cell migration and invasion." (PMID 29113337, 2017). "It has been reported previously that CTNND1, EZH2, BCL2L2, CDH2, VIM, and EGFR have positive correlation to proliferation, invasion, and poor prognosis of gastric cancer." (PMID 28694563, 2017). "Stable over-expression of miR-584-3p resulted in increased binding of AGO2 and epigenetic markers EZH2, EHMT2, H3K27me3 and H3K9me2, and decreased binding of YY1 to MMP-14 promoter in gastric cancer cells, which was attenuated by knockdown of AGO2." (PMID 28827574, 2017). "In contrast, a study in gastric cancer detected that LINC00152 can bind and recruit the PRC2 subunit EZH2 to p15 and p21 promoters which induces their silencing via H3K27me3 modification." (PMID 28536419, 2017). "Here, another possible feedback mechanism and clinical significance of EZH2 and STAT3 were investigated in gastric cancer (GC)." (PMID 27938379, 2016). "We demonstrate that the lncRNA MALAT1 recruits EZH2 to repress PCDH10 and promotes gastric cancer metastasis." (PMID 26871474, 2016). "The results revealed that the knockdown of EZH2 significantly inhibited the proliferation and invasion of the SGC7901 cells, which resembled the suppressive effects of miR-217 overexpression in gastric cancer cells." (PMID 25869101, 2015). "Finally, based on the expression data of four gene markers (DACT1, EZH2, PAK2, PSPC1), we constructed a staging prediction model for 953 gastric cancer samples (319 early, 497 intermediate, and 137 advanced)." (PMID 40959076, 2025). "Furthermore, the oncogenic lncRNA AGAP2-AS1, which is transcriptionally activated by SP1 in gastric cancer cells, forms a complex with LSD1 and EZH2 to repress E-cadherin mRNA expression." (PMID 41229433, 2025). "The prognostic significance of EZH2 and H3k27me3 protein overexpression in gastric cancer has been elucidated, demonstrating a negative correlation between H3K27me3 levels and overall survival in GC patients." (PMID 38542354, 2024). "Finally, miR-625-5p/NFIX, miR-124-3p/EZH2, miR-625-5p/STAT3 and miR-29b/KDM2A are other molecular axes regulated by LINC00511 in gastric cancer." (PMID 37124625, 2023). "Recent studies also clarify that the function of G9A in gastric cancer metastasis or the function of EZH2 in hematopoiesis is independent of their methyltransferase activity." (PMID 37673879, 2023). "Given the many effects of EZH2 in gastric cancer, there are no studies to comprehensively describe this mechanism." (PMID 36672374, 2023). "Although CDK5-EZH2 crosstalk has not been analyzed in gastric cancer, it is possible that CDK5 degrades nuclear EZH2 in gastric cancer, triggering tumor-suppressive pathways." (PMID 37993880, 2023).